VDR (vitamin D receptor)
Diseases named in the same sentence as VDR in open-access papers (continued):
Sharing a sentence is not in itself a finding about the gene and the disease.
periodontitis (continued). "Specific SNPs within RUNX2, CAMTA1 and VDR genes were associated with diversity metrics with no genome-wide associations detected for periodontitis severity or Mets components at p < 10−7." (PMID 38068972, 2023). "A systematic review points to single nucleotide polymorphisms in the Vitamin D Receptor (VDR), the Fc‐γRIIA, and the Interleukin‐10 (IL10) as having the highest level of evidence for a role in periodontitis so far, although many more genes are likely to be involved in different populations." (PMID 35913467, 2022). "In addition, a cross-sectional study showed through gingival samples that periodontitis patients exhibited lower levels of VDR and fewer fibroblast cells with higher inflammatory cell infiltration compared with healthy periodontal individuals." (PMID 32438644, 2020). "This research had clear strengths, such as investigating the influence of geographic area(s) on periodontitis and VDR ApaI risk; however, several shortcomings should be taken notes." (PMID 31763010, 2019). "In recent years, many studies have tried to elucidate the connection between VDR gene ApaI polymorphism and periodontitis, but so far there is no consensus." (PMID 31763010, 2019). "Many studies have tried to elucidate the connection between vitamin D receptor (VDR) gene (ApaI) polymorphism and periodontitis; however, so far there is no consensus." (PMID 31763010, 2019). "Based on the overall analysis, the VDR ApaI polymorphism was not due to the risk of periodontitis in all models." (PMID 31763010, 2019). "A previous meta-analysis has suggested that vitamin D receptor (VDR) gene Taq-I and Fok-I polymorphisms may increase chronic periodontitis, specifically in Asians." (PMID 26688601, 2015). "Specific genetic polymorphisms, such as those in Interleukin-1 (IL-1), IL-6, IL-10, Fcγ receptors (FccR), Vitamin D receptor (VDR), and TNF-α genes, have been shown to be connected with periodontitis." (PMID 40406516, 2025).
lung cancer (41 papers, 2011 to 2025). A malignant neoplasm involving the lung. "Studies confirm VDR overexpression in lung cancer and its association with poor prognosis in EGFR-mutated NSCLC patients." (PMID 40872626, 2025). "In the context of lung cancer, the VDR was formerly associated with better survival outcomes in lung cancer patients, while also showing the antiproliferative effect of the receptor in cell lines." (PMID 38928369, 2024). "Other studies showed that not only should the VDR gene polymorphism phenomenon be considered responsible for an increased risk of lung cancer but also individuals’ ethnicity in corroboration with this genetic diversity." (PMID 38928369, 2024). "To date, there are significant associations between VDR polymorphism and several types of cancer, but the data on the involvement of VDR polymorphism in lung cancer are still conflicting." (PMID 38928369, 2024). "In this review, our aim was to emphasize the importance of VD-dependent proteins and the VD receptor (VDR) in lung pathology and propose a new model of research for the prognostic accuracy of the risk of developing lung cancer." (PMID 38928369, 2024). "Genetic variations in the VDR gene, particularly the polymorphisms Taql, Apal, Bsml, Fokl, and Cdx2, have been associated with an increased risk of lung cancer." (PMID 38928369, 2024). "This review contributes to the awareness of the role of VD, VD-dependent proteins, and VDR gene variation in lung cancer risk." (PMID 38928369, 2024). "On the other hand, it has been reported that increased expression of VDR in lung cancer is associated with better survival." (PMID 36986255, 2023). "It is possible that VDR polymorphisms represent a genetic susceptibility factor for lung cancer, but further studies should be conducted to validate this association." (PMID 36101414, 2022). "In the current study, we appraised expression of VDR and these lncRNAs in lung cancer tissues and ANCTs to evaluate the role of VDR-associated lncRNAs in this type of human malignancy." (PMID 32514489, 2020). "Future studies are needed to address the mechanism for the observed association between relative expression of VDR in tumoral tissues versus ANCTs and sex of lung cancer patients." (PMID 32514489, 2020). "We genotyped 296 SNPs in CYP2R1, CYP27A1, CYP27B1, CYP24A1, and VDR and observed associations between 27 SNPs and lung cancer status after the adjustment for age, gender, and race, all of which had passed the Hardy–Weinberg equilibrium assessment." (PMID 29726119, 2018). "Eighty‐nine percent of the associated SNPs were located in CYP24A1 and VDR, indicating enrichment of genetic variation in the vitamin D signaling cascade associated with lung cancer in those pivotal genes." (PMID 29726119, 2018). "Therefore, in this review, our aim was to investigate the relationship between VDR single-nucleotide polymorphisms in humans and the degree of risk for developing lung cancer." (PMID 38928369, 2024). "However, the relationship between VDR polymorphisms and lung cancer risk remains complex and requires further investigation." (PMID 38928369, 2024). "Moreover, the researchers found that the risk of lung cancer increased with the number of VDR gene variations present in an individual." (PMID 38928369, 2024). "Consequently, Cdx-2, Bsm1 Taq1, and Fok1, which are VDR polymorphisms, were found to be the alterations with the highest correlations with lung cancer development." (PMID 38928369, 2024). "Similarly, VDR (BsmI: rs1544410) had a positive effect on lung cancer risk when subjected to allelic and recessive models." (PMID 38482381, 2024). "Furthermore, VDR (Taq1: rs731236) showed a decreased risk of lung cancer in the allelic, homozygous, and recessive models." (PMID 38482381, 2024).
lung cancer (continued). "Particularly, recent studies suggested that a higher expression of VDR may be associated with better survival rates in lung cancer patients, while in some samples taken from lung tumoral sites, a lower expression of VDR was observed." (PMID 36101414, 2022). "Among these genetic alterations, which may contribute to lung cancer development, researchers have recently considered the gene encoding for the vitamin D receptor (VDR)." (PMID 36101414, 2022). "The association between vitamin D/VDR status and lung cancer depends on tumor type and staging." (PMID 36101414, 2022). "Also regarding lung cancer, Increased VDR expression in lung adenocarcinoma is associated with improved survival." (PMID 33906311, 2021). "Increased expression of VDR in lung cancer is associated with better survival." (PMID 34836039, 2021). "Furthermore, lung carcinogens are highly inflammatory and studies in Tunisia, for example, identified alterations in inflammatory genes- TNF-α, IL8, IL17A, IL17F, CCR2, and VDR Fok1 (rs2228570) and ApaI (rs7975232) that predispose to lung cancer." (PMID 33659210, 2020). "The effects of VDR in the pathogenesis of lung cancer has been further highlighted by the observed associations between several single nucleotide polymorphisms within this gene and risk of lung cancer." (PMID 32514489, 2020). "Additionally, genotyping of 296 SNPs in the same subjects resulted in findings that 27 SNPs, predominantly in CYP24A1 and VDR genes, were significantly associated with lung cancer status, affected mRNA expression, and modulated vitamin D levels." (PMID 29726119, 2018). "However, while epidemiological studies with lung cancer have not been entirely convincing, studies using animal models have found that vitamin D-deficient mice and VDR knockout mice have enhanced tumor growth in many tumor types including lung cancer." (PMID 23896653, 2013). "We hypothesized that associations between VDR polymorphisms and prognosis may be observed not only in specific cancers such as breast and lung cancer but also in other kinds of cancers." (PMID 22242137, 2011). "This provides evidence that VDR gene variations may be an important factor in lung cancer risk." (PMID 38928369, 2024). "The anti-cancer actions of vitamin D are primarily mediated through its binding to the vitamin D receptor (VDR), a nuclear receptor widely expressed in various tissues, including lung epithelial cells and lung cancer cells." (PMID 41003423, 2025). "Previous studies have reported that VDR knockout (VDR−/−) mice exhibit significantly reduced metastatic lung cancer growth, likely due to increased serum concentrations of 1,25(OH)2D3." (PMID 40872626, 2025). "This conclusion can aid better personalized medicine for lung cancer management, while further assessment for genetic variants of CYP3A4, CYP27B1, CYP24A1, GC, and VDR is still required to address more robust evidence." (PMID 38482381, 2024). "Our meta-analysis revealed the lack of association of CYP2R1 (rs10741657), CYP27B1 (rs3782130), CYP27B1 (rs10877012), CYP24A1 (rs6068816), CYP24A1 (rs4809960), CYP3A5 (rs776746), GC (rs7041), GC (rs4588), and VDR (ApaI: rs7975232) with lung cancer." (PMID 38482381, 2024). "Further studies on a larger sample size, taken continuously over the period of the treatment, would offer much-needed information on the evolution of vitamin D3 and VDR levels and their post-treatment prediction power on lung cancer patient outcomes." (PMID 36101414, 2022). "The GO analysis for these differential genes revealed that vitamin D receptor signaling and receptor tyrosine kinases signaling pathway were activated in resistant lung cancers." (PMID 35551652, 2022). "Significantly higher levels of the VDR were observed in lung cancer tissues compared to normal lung tissues taken from patients." (PMID 35631448, 2022).
lung cancer (continued). "The analysis of VDR expression showed a significant increase in the level only in NCI-H1299 lung cancer cells after treatment with PRI-2191 and when PRI-2191 was used with RESV." (PMID 33652978, 2021). "KRAS-mutant lung cancer cells are refractory to 1,25(OH)2D3 due to perturbations in key determinants of vitamin D signaling, such as low levels of VDR and elevated expression of CYP24A1." (PMID 32183160, 2020). "Previous studies have detected expression of vitamin D receptor (VDR) in lung cancer tissues and reported significant of this gene in determination of patients' survival." (PMID 32514489, 2020). "The observed expression of VDR in the majority of tested lung cancer cells and a significant number of clinical samples has indicated the susceptibility of these cells to the differentiating effects of vitamin D." (PMID 32514489, 2020). "In the present investigation, we appraised expression of VDR and five related lncRNAs in lung cancer tissues and ANCTs." (PMID 32514489, 2020). "More recent studies have shown correlation between high VDR expression and better patients' outcome in lung cancer." (PMID 32514489, 2020). "Of the 27 observed associations with lung cancer, 89% of the SNPs were located in CYP24A1 and VDR genes, and several of those SNPs were found to significantly modulate vitamin D3 levels." (PMID 29726119, 2018). "We further genotyped 296 SNPs in the same subjects (N = 761) in CYP2R1, CYP27A1, CYP27B1, CYP24A1, and VDR genes directly involved in vitamin D metabolism, with an objective to elucidate variants that may modulate vitamin D levels, thereby potentially explaining their associations with lung cancer." (PMID 29726119, 2018). "Among the 19 cases of EGFR mutant lung cancer that were identified, we observed variation in VDR expression and cell morphology." (PMID 26654942, 2016). "Using NSCLC cell lines and publically available lung cancer cell line microarray data, we identified a relationship between VDR expression, 1,25(OH)2D3 sensitivity, and EMT phenotype." (PMID 24217116, 2013). "An evaluation of the expression of the VDR related to lncRNAs is relevant in lung cancer." (PMID 38928369, 2024). "In addition, both VDR (Fok1: rs2228570) and VDR (Cdx-2: rs11568820) displayed a protective role in lung cancer development in the heterozygous and dominant models." (PMID 38482381, 2024). "The results indicated that polymorphisms in the VDR gene are associated with a greater risk of lung cancer compared to those without such variations." (PMID 38928369, 2024). "Moreover, it has been shown that expression of the CYP24A1, CYP27B1, and VDR genes in lung cancer is affected by tumor differentiation and characterization." (PMID 36986255, 2023). "Several studies have shown that patients with low levels of vitamin D may be more prone to developing lung cancer; moreover, low levels of vitamin D and the variation of VDR serum levels were also found in lung cancer, as well as in other cancer types." (PMID 36101414, 2022). "From the findings of various reports, it can be demonstrated that VDR expression is deregulated in lung cancer cells and tissues, and using specific agonists for VDR may help to overcome lung cancer by inhibiting tumor cell growth and progression." (PMID 35631448, 2022). "Furthermore, vitamin D3 levels are modulated by VDR genetic variation and are inversely correlated with lung cancer status." (PMID 36101414, 2022). "A study showed that the VDR is often found on the mRNA level in lung cancer cell lines." (PMID 35631448, 2022). "RESV augmented VDR expression in a few lung cancer cell lines, which suggests that this compound may influence the vitamin D signaling in lung cancer cells, leading to an increase in vitamin D activity when used in the combination regimens." (PMID 33652978, 2021). "Thus far, we know that the genetic expression of CYP24A1, CYP27B1, and VDR in lung cancer is affected by tumor differentiation and characterization." (PMID 34836039, 2021).
lung cancer (continued). "As nuclear expression of VDR has been linked with better survival in NSCLC, the observed different patterns of VDR expression between males and females in the current study are in accordance with the better prognosis of lung cancer in females." (PMID 32514489, 2020). "25D3 may be converted by lung cancer cells to 1,25D3, which binds with high affinity to VDR to elicit downstream signaling." (PMID 26654942, 2016). "To fill this knowledge gap, we determined vitamin D receptor (VDR) expression in human lung tumors using a tissue microarray constructed of lung cancer cases from never-smokers (where EGFR gene mutations are prevalent)." (PMID 26654942, 2016). "Nonetheless, these data demonstrate for the first time that human EGFR mutant lung cancers express nuclear VDR protein and may be vulnerable to the anti-cancer activity of vitamin D3." (PMID 26654942, 2016). "Colon, breast, and lung cancer have all demonstrated downregulation of expression of VDR when compared to normal cells and well-differentiated tumors have shown comparably more VDR expression as measured by immunohistochemistry when compared to their poorly differentiated counterparts." (PMID 23533810, 2013). "Three genes (ALDH3A1, VDR and CHKA) are associated both with ATII physiology and lung cancers." (PMID 21489244, 2011). "Not only are VD and the VDR particularly important in lung cancer management but also vitamin D-dependent proteins, such as calbindins, calretinin, and S100-G, which are crucial in calcium ion binding and may impact lung cancer." (PMID 38928369, 2024). "Secondly, this unbalanced ratio favoring the nuclear presence of the receptor in advanced lung cancers could be a sign of potential or actual activity of VD signaling pathways since the VDR must be transferred to the nucleus for the main VD-cascade reactions to begin and function correctly." (PMID 38928369, 2024). "The pattern ‘CEGCKGFF’ appeared in 10% of lung cancer cases, specifically in the proteins RARB and VDR, and was also found in NR1I2 and PPARG within the treatment dataset." (PMID 40334012, 2025). "For instance, VDR can bind the VDRE in the promoter of Let-7a-2 and promote its expression in lung cancer cells (A549)." (PMID 39334706, 2024). "Vitamin-D receptor(VDR) mRNA is overexpressed in neuroblastoma and carcinomas of lung,pancreas, and ovaries and predicts poor prognoses." (PMID 35404047, 2022). "The current investigation potentiates VDR and LINC00346 as possible participants in the pathogenesis of lung cancer." (PMID 32514489, 2020). "Vitamin D receptor (VDR), a critical player in vitamin D signaling axis, is highly expressed in EGFR-mutant lung cancer cells, making them intrinsically sensitive to 1,25(OH)2D3." (PMID 32292420, 2020). "Taken together, the current investigation potentiates VDR and LINC00346 as possible participants in the pathogenesis of lung cancer." (PMID 32514489, 2020). "To determine if VDR protein is present in EGFR mutant NSCLC, we utilized a lung cancer tissue microarray (TMA) constructed within the Pathology Resource Network at Roswell Park Cancer Institute." (PMID 26654942, 2016). "In lung cancer, HRC and VDR expression were dramatically increased and downregulated, respectively." (PMID 35631448, 2022). "Correlation between VDR and EMT Signature Genes in lung cancer cell lines." (PMID 24217116, 2013).